ATF4 (activating transcription factor 4)
Diseases named in the same sentence as ATF4 in open-access papers (continued):
Sharing a sentence is not in itself a finding about the gene and the disease.
cancer (continued). "In addition to the role of ATF4 as a downstream effector of Nrf2 in cancer cells, it is increasingly reported that the direct interaction of Nrf2 and ATF4 is involved in gene expression." (PMID 32079324, 2020). "Cancer cells, which are exposed to many stresses, require ATF4 for survival and proliferation." (PMID 32938922, 2020). "In addition, PERK enhances cell migration and invasion in vitro and in vivo, and ATF4 target gene expression correlates with EMT gene signature in cancers including lung cancer." (PMID 32576923, 2020). "Interestingly, cancer cells treated with the nelfinavir showed reduced mTOR activity and increased ATF4 and SESN2 expression levels." (PMID 31546746, 2019). "Because the induction of Chop in cancer cells undergoing ER stress has been related with the activation of Perk and a subsequent upregulation of Atf440, we analyzed the effect of Perk in the expression of Chop and Atf4 in stimulated T cells." (PMID 30894532, 2019). "In addition, activation of PI3K/AKT by K-Ras stimulates expression of NRF2, which in turn transactivates ATF4 in promoting cancer cell survival and growth upon amino acid deprivation." (PMID 31064130, 2019). "Interestingly, ATF4 has been described as a potential poor prognostic biomarker in this cancer type." (PMID 31064137, 2019). "The enhancement of PERK/ATF4 signaling is mediated by ROS generation in apoptosis of cancer cells." (PMID 29543750, 2018). "In addition, the PERK-eIF2α-ATF4 signaling pathway in cancer cells mediates the upregulation of VEGF-A transcription." (PMID 30081573, 2018). "Phosphorylated eIF-α, the upstream ATF4 regulator, was only increased in the cancer cell lines." (PMID 29991718, 2018). "The results suggest a conditional regulation of KRT16 gene by ATF4 that may be inhibited in normal cells, but engaged during cancer progression." (PMID 29420561, 2018). "ATF4, a well-known hallmark of UPR activation, is highly expressed in the cancer cells." (PMID 29991718, 2018). "Importantly, in both cell models, cancer cell death appeared to occur via reactivation of the EIF2A/ATF4/CHOP pathway." (PMID 29541451, 2018). "Mechanisms that regulate PeIF2α-induced ATF4 mRNA translation towards cell survival and cancer cells resistance to drugs remained largely unknown." (PMID 29062139, 2017). "We found that treatment of cancer cells with ER stress agents exemplified by sorafenib (Sor; a chemotherapeutic agent used to treat hepatocellular carcinoma), induces the formation of SG that sequester a fraction of ATF4 mRNA in a repressed form." (PMID 29062139, 2017). "ATF4 is a master stress-induced transcription factor that orchestrates gene expression in cells treated with various ER stress inducers including those used to treat cancers." (PMID 29062139, 2017). "In the TRAIL-independent pathway, ONC201 induces ER stress responses via ATF4 to kill cancer cells." (PMID 28423492, 2017). "We made the hypothesis that a similar adaptation to amino acid deprivation involving a low level of expression of ATF4 could be observed in a cancer cell line." (PMID 28460466, 2017). "Finally, we have been able to establish that this feature of a low level of ATF4 expression leading to amino acid deprivation resistance occurred also in, at least, one cancer cell line." (PMID 28460466, 2017). "In the same view, Atf4 induction by prolonged stress exposure triggers apoptosis in cancer cells; so, the enhancement of Atf4 protein expression evidenced in TRPV1 KO thymocytes, may lead to increased susceptibility of thymocytes to apoptotic stimuli." (PMID 29207602, 2017). "However, ATF4 knock-down limited LC3B induction after bortezomib treatment, confirming the importance of ATF4 as a mediator of the compensatory response in ER-positive cancer cells." (PMID 29145850, 2017).
cancer (continued). "Interestingly, oroxylin A was reported to activate UPR in HepG2 cancer cells by the PERK/eIF2α/ATF4 pathway, but excessive activation of this pathway resulted in the activation of CHOP and induced cell death." (PMID 27195463, 2016). "Deeper investigation of selected hits from the screen showed that the transcription factor ATF4 drives ULBP1 gene expression in cancer cell lines, while the RNA-binding protein RBM4 supports ULBP1 expression by suppressing a novel alternatively spliced isoform of ULBP1 mRNA." (PMID 26565589, 2015). "ATF4, ATF3, and CHOP were downregulated in PKCδ-deficient cancer cells." (PMID 26188905, 2015). "Together, these results suggest that Atf4 mediates a shift from a metabolism based on oxidative phosphorylation to one more heavily reliant on glycolysis, reminiscent of aerobic glycolysis or the Warburg effect observed in cancer and other proliferative cells." (PMID 25681259, 2015). "Previous studies have suggested that targeting this ATF4‐mediated stress response may provide an effective cancer therapy." (PMID 25693838, 2015). "Alternatively, cancer cells may rely on ATF4-mediated stress mechanisms to bypass these inhibitors." (PMID 40598593, 2025). "However, whether ALKBH5 or FTO are required for ATF4 mRNA translation in chemotherapeutic-treated cancer cells to promote resistance is still unknown." (PMID 39199320, 2024). "Furthermore, COP significantly reduced ATF4 mRNA levels in cancer cells." (PMID 38994891, 2024). "However, the efficacy of ferroptosis in cancer is invariably offset by the adaptive ATF4 response." (PMID 38903991, 2024). "In a therapeutic context, we further provide evidence that targeting the phosphorylation of eIF2 to induce cell death in leukemic cells may be a viable strategy for future therapies, as some potential anti-cancer drugs act via the eIF2/ATF4 signaling pathway, which in turn promotes apoptosis." (PMID 39223663, 2024). "In addition, ATF4 is frequently up-regulated in cancer cells." (PMID 38838145, 2024). "Hence, the pharmacologic targeting of GCN2, an ATF4 upstream regulator, might have benefits against Mic60-low-expressing cancer." (PMID 37525297, 2023). "However, research has found ATF4 to increase cancer cell line proliferation." (PMID 36825279, 2023). "The higher transcript levels of the key genes in the Atf4 pathway, such as Trib3 and Asns, which were observed in the ETOH-BKO livers led us to measure 4-EBP1 (EIF4EBP1), as it is a critical ATF4 gene target that is implicated in protein synthesis, metabolic and stress adaptations, and cancer." (PMID 37569418, 2023). "We investigated whether ATF4 expression is relevant in human cancers." (PMID 36739602, 2023). "In addition, HDAC4 plays a role in regulating endoplasmic reticulum stress-induced apoptosis by binding to and inhibiting the activity of activating transcription factor 4 (ATF4), which is a stress-induced transcription factor that plays an important role in cancer cell survival." (PMID 36644540, 2023). "Given its integral role in reducing cell stress, previous work has identified ATF4 as key protein involved in metastatic processes such as migration and resistance to anoikis, suggesting that its expression is not only critical to cell survival, but also to cancer progression." (PMID 35847893, 2022). "Furthermore, ATF4 was demonstrated to induce apoptosis in cancer cell lines independently of CHOP." (PMID 34295932, 2021). "In conclusion, targeting ATF4/Noxa axis could be a promising strategy for cancer treatment." (PMID 33995110, 2021).
cancer (continued). "Also in accordance with our discovery, other reports suggested that GCN2/ATF4 signaling plays a role in the survival and proliferation of cell lines and cancer xenografts under suboptimal growth conditions as a result of amino acid/nutrient deprivation and unbalanced protein synthesis." (PMID 34180400, 2021). "With cell proliferation assays, colony formation assays, Transwell assays, gemcitabine survival IC50 assays, and sphere formation assays, we demonstrated that silencing the expression of ATF4 could inhibit proliferation, migration, cancer stemness, and gemcitabine resistance." (PMID 33782384, 2021). "ATF4 is overexpressed in many types of cancers and regulates the expression of adaptive genes responsible for reprogramming the metabolic pathways that enable cancer cells and stromal cells to tolerate various stresses, including hypoxia, glucose and amino acid deprivation." (PMID 33466790, 2021). "Therefore, ATF4 may function to promote metabolic homeostasis and enable cancer cell survival under certain stress conditions." (PMID 34709767, 2021). "Further insight into ATF4 activation may shed light on understanding the context of how these transcription factors respond to stress and the biological outcome they ultimately trigger in both normal and cancer cells." (PMID 34630117, 2021). "Hence DENR•MCTS1 appear to promote ATF4 translation in a broad range of cancer cells." (PMID 32938922, 2020). "In addition, PERK/eIF2alpha/ATF4 activation also can potentiate apoptosis in cancer cells." (PMID 31395860, 2019). "In addition, ATF4 promotes metastasis by reducing anoikis of cancer cells in suspension." (PMID 30824833, 2019). "However, little is known about the role of ATF4 or HSPA5 in the RET signalling pathway in cancer." (PMID 31534554, 2019). "Therefore, decreasing ATF4 expression may be one important mechanism for cancer cells to survive under prolonged amino acid deprivation." (PMID 28460466, 2017). "In fact, ER stress might be used to obtain an anti-cancer effect: tunicamycin potentiates cisplatin anti-cancer efficacy, inducing accumulation of unfolded proteins in the ER, while cannabinoids activate the ER stress-related genes ATF-4 and TRB3, inducing pancreatic tumor cell death." (PMID 28913175, 2017). "However, factors (e.g. RNA-binding proteins and specific eIFs) responsible for maintaining the translation of ATF4 mRNA allowing the resistance of cells to stress (e.g. resistance of cancer cells to therapeutic agents), remain largely unknown." (PMID 29062139, 2017). "To elucidate whether the activation of the eIF2α-ATF4 pathway per se was sufficient for the increases in xCT expression and cisplatin resistance, we treated the cancer cells with salubrinal (an eIF2α phosphatase inhibitor) to elevate the activity of this pathway." (PMID 27708226, 2016). "However, the identification of differential correlation structure provides the first integrated hypothesis that suggests MAX could modulate the co-expression of ATF4 and CLOCK, leading to differential cancer drug susceptibility." (PMID 26539209, 2015). "During stress, increased ATF4 levels enhanced ASCT2 expression, enabling cancer cells to enhance glutamine uptake and sustain growth." (PMID 40223274, 2025). "ATF3 and ATF4, belonging to the activating transcription factor (ATF) family, are involved in critical cancer biology pathways and mediate cellular responses to stress." (PMID 40722679, 2025). "GCN2 is upregulated in a wide range of cancer types and the GCN2/p‐eIF2α/ATF4 pathway is essential to cancer growth in response to nutrient deprivation." (PMID 38949989, 2025). "Cancer cells can exploit UPR to promote proliferation and metastasis, mainly via the downstream transcriptional factors XBP1s, ATF4, and cleaved ATF6." (PMID 41193471, 2025).
cancer (continued). "Since AA restriction upregulates ATF4 in activated T cells and TRIB3 overexpression is consistently observed across various cancers, we employed the 2xAARE system from the TRIB3 gene to create an ATF4-based strategy that restricts CAR expression to the TME." (PMID 40335738, 2025). "In cancer cells, MAPK signaling activates ATF4 during asparagine restriction, regulating genes involved in amino acid metabolism and stress response." (PMID 39817770, 2025). "As previously stated, PERK enhances the expression of ATF4 and CHOP, facilitating growth, progression, and immune evasion in cancer under ER stress." (PMID 40547943, 2025). "Taken together, we found that HDACi synergize with Gem in eliciting ER-stress and activating all three major UPR branches in PDAC cancer cells, with a preference for the PERK/ATF4 and IRE1/XBP1 arms and with a weaker activation of the ATF6 arm." (PMID 40287668, 2025). "Decursin increases ROS levels and upregulates ATF4, PERK, and CHOP, thereby enhancing the expression of DR5 and sensitizing cancer cells to TRAIL-induced apoptosis." (PMID 41476609, 2025). "In various cancer models, curcumin can inhibit the pro-survival PERK-eIF2α-ATF4 pathway, thereby promoting apoptosis and enhancing the efficacy of conventional therapies." (PMID 41009381, 2025). "Mechanistically, we uncovered that DT-061-mediated modulation of PP2A induced the ISR through the dephosphorylation of TFE3, resulting in chronic upregulation of ATF4 and CHOP to inhibit stress recovery and induce cell death in cancer cells." (PMID 39349971, 2024). "ROS release and mitochondrial dysfunction promote ER stress and apoptosis by upregulating ATF4 and CHOP in various cancer types." (PMID 39770941, 2024). "PRMT1 binds to ATF4 in a BTG1-dependent manner, and PRMT1 methylates ATF4, promoting transcription of some target genes of ATF4, leading to increased apoptosis in cancer cells." (PMID 38326807, 2024). "Cancer-related genes such as CXCR4, MMP7, CDC20 and CDK6, and unfolded protein response (UPR)-related genes such as ATF3, ATF4, XBP1 and CHOP, showed significant differences in expression in the indicated cells." (PMID 38263248, 2024). "Glutamine consumption is enhanced in cancer cells, and high expression of SLC1A5 (ASCT2), the major glutamine transporter, is correlated both to the levels of MYCN as well as the activating transcription factor 4 (ATF4) in NB cells." (PMID 39101440, 2024). "Strikingly, despite the PERK phosphorylation attenuation at 24 h post washout, all targets canonically downstream of eIF2α phosphorylation including ATF4, CHOP, and GADD34 remained transcriptionally and translationally activated specifically in cancer cells." (PMID 39349971, 2024). "Highly expressed activating transcription factor 4 (ATF4), a major effector of the PERK pathway, has been found in various cancers." (PMID 39090107, 2024). "Triggering UPR-mediated ER stress in cancer cells contributes to cell death, of which CHOP and ATF4 act as the downstream gene of UPR sensors." (PMID 39850563, 2024). "ATF4 itself can promote apoptosis by directly upregulating NOXA and PUMA expression, leading to cancer cell apoptosis." (PMID 39007268, 2024). "In summary, these findings indicate that DT-061 mediates TFE3 dephosphorylation via PP2A, subsequentially promoting the transcriptional activation of ATF4 and CHOP that drives irreversible ISR phenotypes and triggers pro-death signals in cancer cells." (PMID 39349971, 2024). "It has been reported that PERK/ATF4 induces transcription and expression of the ubiquitin ligases SIAH1/2 in cancer cell lines.To identify the link among PERK, ATF4, SIAH2 and HIPK2, knockdown of genes by siRNA was carried out." (PMID 37268944, 2023). "The antioxidant TA scavenges excess mROS in cells and alters the expression of PERK, IRE1, and their regulatory proteins (ATF4, Bip, and PDI) to induce ER stress and apoptosis of cancer cells." (PMID 37885044, 2023).
cancer (continued). "Depletion of ALKBH5 increased the levels of the UPR sensor proteins PERK, ATF4, ATF6, and IRE-α in normal and cancer cell lines." (PMID 37174684, 2023). "Lysine demethylase 4C interacts with ATF4 and mediates the epigenetic modification required for gene expression activation of the SSP genes in various cancer cell lines and in xenografts in mice." (PMID 37949226, 2023). "Upon targeted and conventional cancer therapies, cancer cells often induce stress response to survive the cancer treatment and generate drug tolerance via heme-regulated inhibitor (HRI) kinase-ATF4 signaling." (PMID 36830722, 2023). "Considering the dysregulated and reprogrammed metabolic environment in cancer cells, it needs deep understanding for the PERK/ATF4/CHOP in crosstalk between ER stress and apoptosis." (PMID 36721107, 2023). "Within the cancer-enriched constituent enhancers of SE60, we found SOX4, ATF4, and YY1 as the top three predicted transcription factors." (PMID 35869079, 2022). "Previous studies reported that anti-cancer agents (e.g., MLN4924) transcriptionally activated ATF4 by inducing ER stress, and subsequently induced CHOP-mediated DR5 transcription and caspase 8-mediated extrinsic apoptosis." (PMID 35754502, 2022). "We found significantly reduced levels of all three proteins in the cancer tissues when compared to the matching normal pancreatic tissues (p = 0.0112 for REDD1, 0.0095 for ATF4, and 0.0283 for TXNIP)." (PMID 38089448, 2022). "Depletion of ATF4 (activating transcription factor 4) has also been shown to increase erastin-induced ferroptosis and RSL3-induced ferroptosis in several cancer cell lines." (PMID 35075250, 2022). "As already reported for other cancer cell types under serine starvation, we observed that PHGDH re-expression was regulated at the transcriptional level following ATF4 upregulation at day 4, in serine/glycine-free medium." (PMID 35931688, 2022). "Cancer cells alleviate ER-stress by activating UPR characterized by the expression of BiP, XBP1-s, CHOP, and ATF4." (PMID 35436985, 2022). "The reduced sensitivity to OXPHOS inhibition of cancer cells upon NNMT overexpression and DNMT1 knockdown was also reflected by attenuated ATF4 upregulation and p‐S6 downregulation when treated with OXPHOS inhibitors (Gboxin, Oligomycin A, and Berberine)." (PMID 36382559, 2022). "The co-targeting of glutaminolysis and ATF4 is synergistic in suppressing CRC growth, inferring a strategy for cancer treatment." (PMID 36289851, 2022). "Interchromosomal interactions have been demonstrated between SOX9 and the lncRNA CISTR-ACT gene or the ATF4 and FIRRE genes to serve biological processes including mammalian development and differentiation, as well as cancer stemness." (PMID 34707247, 2022). "Their ability to stimulate a UPR response has been evaluated in different cancer cell lines, and ticlopidine resulted in being more effective in inducing the expression of UPR effector proteins (i.e., BIP, ATF4 and CHOP)." (PMID 35889200, 2022). "Therefore, RPL41 may have potential as an anti-ATF4 agent for cancer therapy." (PMID 34993140, 2021). "RPL41 induces the phosphorylation and relocalization of the activating transcription factor 4 (ATF4) from the nucleus to the cytoplasm, resulting in its subsequent proteasomal degradation in human cancer cells." (PMID 34831461, 2021). "At the transcriptional level, SLC7A11 is upregulated in cancer cells by transcription factors, such as nuclear factor erythroid 2-like 2 (NFE2L2/NRF2) and activating transcription factor 4 (ATF4)." (PMID 34742351, 2021).